IRF1 (interferon regulatory factor 1)
Diseases named in the same sentence as IRF1 in open-access papers (continued):
Sharing a sentence is not in itself a finding about the gene and the disease.
rheumatoid arthritis (7 papers, 2009 to 2023). A chronic, systemic autoimmune disorder characterized by inflammation in the synovial membranes and articular surfaces. "In fibroblast like synoviocytes (FLS), which are implicated in the inflammation in rheumatoid arthritis, TNF-alpha-mediated induction of IRF1 leads to induction of inflammatory mediators, such as IFN-gamma." (PMID 34211464, 2021). "Moreover, expression levels of Irf1 were significantly higher in the synovium of joints with rheumatoid arthritis than in that of those with osteoarthritis." (PMID 24063402, 2013). "Thomas Karonitsch at the Medical University of Vienna, Austria, and colleagues showed that activation of the protein interferon regulatory factor 1 (IRF-1) in human synoviocytes promoted the expression of genes that contribute to sustained synovial inflammation in rheumatoid Arthritis (RA)." (PMID 31285419, 2019).
acute myeloid leukemia (6 papers, 2007 to 2024). Acute myeloid leukemia (AML) is a group of neoplasms arising from precursor cells committed to the myeloid cell-line differentiation. "For example, deletion of the 5q31.1 locus within the IRF1 gene and the occurrence of its inactivating mutations were associated with the development of acute myeloid leukemia and myelodysplastic syndrome in patients." (PMID 38396830, 2024). "Two regulators of NF-κB that have been implicated as tumor suppressor genes, DAPK and IRF-1, have been found to be deregulated and present in many samples obtained from patients with acute myelogenous leukemia (AML)." (PMID 27542251, 2016). "In acute myeloid leukemia, point mutations or deletions of the IRF-1 gene have frequently been detected." (PMID 17319941, 2007). "IRF1 variants lacking exons 2 and 3 were detected in patients with acute myeloid leukemia and myelodysplastic syndrome, while the number of full-length IRF1 variants were reduced." (PMID 38396830, 2024). "IRF1 has been implicated in the pathogenesis of acute myeloid leukemia (AML) and myelodysplastic syndrome (MDS) with aberrations of chromosome 5, where the IRF1 gene is located." (PMID 37889967, 2023).
Arthritis (6 papers, 2014 to 2023). Inflammation of a joint. "It is reported that arthritis was mitigated in interferon alpha/beta receptor alpha chain-deficient mice and interferon regulatory factor-1-deficient mice." (PMID 32164778, 2020). "Here, we show that TNF regulates the expression of the transcription factor interferon regulatory factor 1 (IRF1) in human FLSs as well as in a TNF transgenic arthritis mouse model." (PMID 31285419, 2019). "The affected 5q LOH interval harbors several cytokine genes (including IL-3, IL-4, IL-5, IL-13, and CSF2), a gene associated with arthritis susceptibility (SLC22A4), a DNA repair gene (RAD50), and a gene that promotes Type 1 interferon responses (IRF1)." (PMID 25107306, 2014). "AHR, CAV1, CRP, CXCL2, IRF1, SPP1 and other targets play important roles in the pathogenesis of arthritis and can be used as key targets for the treatment of arthritis." (PMID 37637408, 2023). "Therefore, ADRB2, AHR, CRP, IRF1, PTGS1, SPP1 and other targets can be used as potential targets for CC in the treatment of arthritis, and it is of great significance to explore its role of CC in the treatment of arthritis." (PMID 37637408, 2023). "Similarly, IRF1 was highly expressed in the inflamed synovium in human TNF transgenic (hTNFtg) mice that constitutively overexpress human TNF, and consequently develop spontaneous arthritis." (PMID 31285419, 2019).
cardiac hypertrophy (6 papers, 2015 to 2024). "Cardiac-specific IRF1 overexpression exacerbated pressure overload-induced hypertrophy, ventricular dilatation and dysfunction, whereas cardiac hypertrophy was attenuated in IRF1 knockout mice and rats." (PMID 38665231, 2024). "Notably, cardiac hypertrophy and failure were also observed in kl/kl mice, accompanied by decreased PGC1α expression, increased IRF1 expression, mitochondrial dysfunction, and energy metabolism remodeling." (PMID 32938919, 2020). "To better clarify the direct role of IRF1 in HP-induced alterations, we fed IRF1 knockout (IRF1−/−) mice with HPD for 12 weeks and found that HPD-induced cardiac hypertrophy, HF, downregulated PGC1α expression and energy metabolism remodeling were significantly attenuated in IRF1−/− mice." (PMID 32938919, 2020). "In this study, we demonstrate that the increase of IRF1 expression can induce energy metabolism remodeling by directly downregulating PGC1α in cardiomyocytes, thus providing new insight into the mechanisms of IRF1-induced cardiac hypertrophy." (PMID 32938919, 2020). "This negative regulation of PGC1α by IRF1 was further confirmed by the finding that knockdown of IRF1 significantly rescued HP-induced downregulation of PGC1α, mitochondrial energy metabolic dysfunction, and cardiac hypertrophy." (PMID 32938919, 2020).
diabetes (6 papers, 2010 to 2025). "These include transcription factors concerned with the control of: adipogenesis (Pparγ, Klf15, Irf1, Creb1, Egr2, Gata3); lipogenesis (Mlxipl, Srebp1c); inflammation (Jun, Stat3); insulin signalling and diabetes susceptibility (Foxo1, Tcf7l2)." (PMID 21187013, 2010). "Another study investigating differential monocyte gene expression in individuals with diabetes identified IRF1, GATA6, SP11, EPAS1, NFKB2, and STATB3 as key affected transcription factors." (PMID 40476695, 2025). "Key examples include IRF1, GATA6, SPI1, EPAS1, NFKB2, and STAT5B, which are involved in immune response, cell differentiation, and metabolic regulation, all of which are critical in diabetes pathogenesis." (PMID 39877357, 2024). "Indeed, IRF1 was increased in retinas during OIR and STZ‐induced diabetes, which paralleled the expression pattern change of Sema4D." (PMID 31943789, 2020).
neuroblastoma (6 papers, 2012 to 2023). Neuroblastoma (NB) is the most common solid, extracranial childhood tumor. "Furthermore, in neuroblastoma cells, Nf-κB was found to synergize with IRF1 in enhancing tapasin." (PMID 30261835, 2018). "For instance, IRF1 and IRF2 interact synergistically to suppress neuroblastoma by regulating apoptotic caspase-7/8 and MHC-I gene expression." (PMID 36498991, 2022). "Overexpression of NF-kB p65 together with Interferon Regulatory Factor 1 was able to restore MHC-1 expression and cellular immune complex formation in neuroblastoma cell lines." (PMID 24116151, 2013).
Autoimmunity (5 papers, 2014 to 2025). The occurrence of an immune reaction against the organism's own cells or tissues. "The transcription factor IRF1 contributes to the development autoimmunity in animal models, and loss of IRF1 tumor suppressor function has been proposed to promote myelodysplasias and the development of myelodysplasia-associated autoimmunity." (PMID 25107306, 2014). "Some of the mutated genes (SLAMF6, IRF1) have previously been associated with autoimmunity." (PMID 28635960, 2017). "For instance, IFN alpha and gamma regulate ER dependent function in antigen presentation, suggesting that the TMEM230/RNASET2/SDC2/IRF1 axis is mis regulated both in autoimmunity and cancer." (PMID 40862725, 2025). "When compared to CVID patients without autoimmunizations, up-regulation of STAT1 and IRF1 gene expression was observed." (PMID 38474381, 2024).
cholangiocarcinoma (5 papers, 2019 to 2024). A carcinoma that arises from the intrahepatic biliary tree (intrahepatic cholangiocarcinoma) or from the junction, or adjacent to the junction, of the right and left hepatic ducts (hilar cholangiocarcinoma). "In cholangiocarcinoma cells, miR-383 overexpression enhanced cell invasion and proliferation by inhibiting IRF1." (PMID 36313570, 2022). "Accordingly, the downregulation of miR-383 resulted in IRF1 overexpression, which inhibited cholangiocarcinoma progression." (PMID 36313570, 2022). "Interferon regulatory factor 1 (IRF1) is a tumor suppressor in cholangiocarcinoma and was reported to be a direct target of miR-383." (PMID 34976192, 2022). "In cholangiocarcinoma patients, lower IRF1 expression in tumor tissues was correlated with tumor progression and poor prognosis." (PMID 36313570, 2022). "MiR-383 supports cholangiocarcinoma cell expansion and migration by inhibiting IRF1 expression." (PMID 36313570, 2022). "IRF1 acts as a tumor inhibitor in cancers, including cholangiocarcinoma." (PMID 36313570, 2022). "We analyzed the expression levels of Type I interferons and ISG genes in the tumor tissues of patients and normal control tissues, revealing a consistent upregulation of ISG genes, including ISG15, MX1, MDA5, IFIT2, IFIT3, IRF1 and IRF7, in the tumor tissues of patients with cholangiocarcinoma." (PMID 38817870, 2024). "In the miR-383/IRF1 pathway, IRF1 is a functional miR-383 target, so a negative correlation was found between the expression levels of IRF1 and miR-383 in cholangiocarcinoma tissues." (PMID 36313570, 2022).
esophageal squamous cell carcinoma (5 papers, 2018 to 2025). Esophageal squamous cell carcinoma (ESCC) is a type of esophageal carcinoma (EC) that can affect any part of the esophagus, but is usually located in the upper or middle third. "This was exemplified through the characterization of long non-coding RNA antisens (lnc-RNA-AS) which can activate the IFN response leading to an anti-proliferative activity at least in part via interferon regulatory factor 1 (IRF1) in esophageal squamous cell carcinoma." (PMID 37180110, 2023). "In esophageal squamous cell carcinoma, up-regulation of GBP2 and IRF-1 as its maintranscriptional regulator proposed it as a possible cancer-related marker (Guimaraeset al., 2009)." (PMID 33211060, 2020). "Wang and colleagues have further investigated the part played by IRFs in esophageal malignancies by measuring patterns of IRF-1 and IRF-2 protein expression in esophageal squamous cell carcinoma (ESCC) and correlating them with the clinical features of this disease." (PMID 29599126, 2018).
gastric adenocarcinoma (5 papers, 2014 to 2022). "miR-23a, which binds to the 3′-UTR of IRF-1 mRNA, is overexpressed in gastric adenocarcinoma, resulting in IRF-1 down-regulation and loss of transcriptional activity, in turn enhancing pro-proliferative and anti-apoptotic conditions." (PMID 29599126, 2018). "A previous study demonstrated that IRF1 is a target of miR-23a in human gastric adenocarcinoma cells." (PMID 25980475, 2015). "Our laboratory previously demonstrated that miR-23a directly targets IRF1 genes and negatively regulates their expression in gastric adenocarcinoma cells." (PMID 25461762, 2014). "For example, miR-23a induces gastric adenocarcinoma formation through silencing IRF1 expression." (PMID 25980475, 2015). "Recently, interferon regulatory factor 1 (IRF1), which is involved in innate antiviral immunity, inflammation, and the pro-apoptotic pathway, was identified as a target of miR-23a to regulate cells growth and apoptosis in gastric adenocarcinoma." (PMID 25461762, 2014). "The somatic mutation of eight risk PRGs (CASP4, GPX4, GSDMC, TLR3, NLRP1, PLCG1, IL18, and IRF1) hardly occurred in PAAD samples but were commonly observed in colon adenocarcinoma (COAD) and stomach adenocarcinoma (STAD) ones." (PMID 35000541, 2022).
H1N1 influenza A virus infection (5 papers, 2017 to 2023). "Its upregulation decreased interferon response through interferon regulatory factor 1 (IRF1) in H1N1 influenza A virus infection." (PMID 37008787, 2023). "Moreover, recent studies revealed that inhibiting IRF1 could facilitate H1N1 influenza A virus infection, while, in contrast, overexpression of IRF1 suppresses AIV and NDV viral yield in chicken cells." (PMID 35159296, 2022). "The H7N9, H7N7 and H5N1 infected mouse lung transcriptome also showed higher levels of CXCL13, IL-6, IFNG, IFNB1, IRF9, IRF1, and TNF compared with 2009 pandemic H1N1 virus infections." (PMID 28558796, 2017).
head and neck squamous cell carcinoma (5 papers, 2020 to 2025). A squamous cell carcinoma that arises from any of the following anatomic sites: lip and oral cavity, nasal cavity, paranasal sinuses, pharynx, larynx, and salivary glands. "Recent studies have indicated that in head and neck squamous cell carcinoma (HNSCC) cells, the knockdown of IRF1 can reduce the expression levels of IFI44L and suppress cell proliferation and invasiveness." (PMID 39737399, 2024).
Insulin resistance (5 papers, 2021 to 2025). Increased resistance towards insulin, that is, diminished effectiveness of insulin in reducing blood glucose levels. "Intriguingly, insulin resistance and impaired glucose metabolism leading to new-onset T2DM have been associated with IRF1 overexpression in PASC." (PMID 41488148, 2025). "IRF1 functions as a mediator of adipocyte inflammatory phenotypes and alters lipid droplet composition of adipocytes, and its overexpression leads to insulin resistance and attenuated lipolysis." (PMID 34869349, 2021). "In addition, impairment of several insulin/IGF signaling pathway genes—relevant to insulin resistance and compromised glucose metabolism—was attributed to increased interferon regulatory factor 1 (IRF1) expression and its observed activity or effect." (PMID 41488148, 2025).
multiple sclerosis (5 papers, 2009 to 2022). A progressive autoimmune disorder affecting the central nervous system resulting in demyelination. "Evidence has also emerged that IRF-1 may play an important role in cell death involving caspase-1 activation, which has been associated with oligodendrocyte pyroptosis in encephalomyelitis and multiple sclerosis." (PMID 31871426, 2019). "IRF1-regulated reactive microglia mediate oligodendrocyte and neuronal cell death in multiple sclerosis, brain injury, and degenerative diseases." (PMID 36498991, 2022). "Caspase-1 contains an IRF-1-binding element, and the caspase-1 activity can be directly modulated by IRF-1 in the development of multiple sclerosis and acute lung injury." (PMID 31871426, 2019). "Likewise, fumarates had differing effects on the expression of key genes that have been linked to multiple sclerosis (e.g., TNFAIP3, CXCL8, IL6, and IRF1)." (PMID 35455458, 2022).
Obesity (5 papers, 2007 to 2025). Accumulation of substantial excess body fat. "Finally, motif analysis revealed that promoter regions open in monocytes from lean subjects at T3 (closed in monocytes from subjects with obesity) harbor binding sites for transcription factors PU.1 and AP-1 and interferon regulators IRF1, IRF3, and IRF8." (PMID 34195568, 2021). "The NF-κB target genes IRF1, STAT1, JUN, HSP90AA1, FOS, and EGR1, were enriched in the pathway of Glucocorticoid receptor regulatory network and homeostasis pointing towards their critical role in obesity." (PMID 31013288, 2019). "Moreover, bulk RNA-Seq revealed an enhanced transcriptional response to LPS at T3 relative to T1 in the lean subjects relative to those with obesity marked by higher expression of pro-inflammatory molecules (IL6, IL1B, TNF) and induction of transcription factors (RELA, IRF1, STAT3)." (PMID 34195568, 2021).
renal fibrosis (5 papers, 2015 to 2023). A final common manifestation of a wide variety of chronic kidney diseases characterized by glomerulosclerosis and tubulointerstitial fibrosis. "In mouse kidneys with fibrosis and inflammatory infiltration, sample sequencing to a depth of 30 million reads and network analysis showed that the top TFs, such as Irf1, Nfkb1, and Stat3, are important drivers of renal fibrosis progression." (PMID 36246123, 2022). "On the other hand, the depletion of IRF1 in mice restricted the progression of renal fibrosis." (PMID 37508555, 2023).
squamous cell carcinoma (5 papers, 2010 to 2023). A carcinoma arising from squamous epithelial cells. "The upregulation of RBL1 and downregulation of IRF1 in the microarray analysis was significant in squamous cell carcinoma but was statistically insignificant in adenocarcinoma." (PMID 24564251, 2013). "Yet, IRF1 is overexpressed in profiling experiments of Squamous Cell Carcinomas, amid other IFN-activated signature genes." (PMID 21072181, 2010). "We found that E2F6, HMGA1, IRF1, and TFDP1 were upregulated and RBL1, SUV39H1, and HNRPD were downregulated or aberrantly expressed in adenocarcinoma and squamous cell carcinoma, which are the sub-types of NSCLC." (PMID 24564251, 2013). "The protein level of PDL1 was significantly correlated with those of IRF1, eIF2α, and ATF4 in the tissues of all subjects and the subgroup of squamous cell carcinoma but not in the normal tissue of adenocarcinoma." (PMID 30305853, 2018). "Therefore, combining the microarray and qPCR results, upregulation of E2F6, HMGA1, IRF1, and TFDP1 and downregulation or no expression of SUV39H1, RBL1, HNRPD can be used as diagnostic markers of NSCLC, and, in particular, adenocarcinoma and squamous cell carcinoma." (PMID 24564251, 2013).
ZIKV infection (5 papers, 2020 to 2023). "Basal and ZIKV infection-induced levels of IRF-1 were similarly fractionated in the case of CD24-low and -high cells, with the only apparent difference being the overall higher level of IRF-1 expression in CD24-low cells (compare lanes 2 and 6)." (PMID 36016357, 2022). "We evaluated the crosstalk between RIG-I and DNA-PKcs during ZIKV infection analyzing the IFN-I/III-inducing transcription factors including IRF1, IRF3, IRF5, IRF7, and p65 (NF-κB subunit)." (PMID 36311766, 2022). "In both cell lines, IRF-1 was upregulated following ZIKV infection (lanes 2 and 4), to signals of 548,000 and 394,000 in CD24-low and –high cells, respectively." (PMID 36016357, 2022). "Interestingly, immune escape by ZIKV infection could be caused by downregulation of prolactin signaling including IRS2, PIK3C3, JAK3, STAT3, and IRF1 as well as mitochondria dysfunction and oxidative phosphorylation in myeloid dendritic cells." (PMID 32287277, 2020). "Type II IFN (IFNγ) are key inducers of proinflammatory cytokines such as IRF1, IFIT1, CXCL10 and crucially, known cellular receptors for ZIKV infection such as AXL, Tyro3, and DC-SIGN." (PMID 35536870, 2022). "Furthermore, we showed ZIKV infection fails to induce IRF1 and IRF3 accumulation to the nucleus in absence of the RNA sensor RIG-I, suggesting DNA-PKcs is not a ZIKV sensor receptor." (PMID 36311766, 2022). "We observed that ZIKV infection induces IRF1 and IRF3, but not IRF5 and IRF7 nuclear accumulation." (PMID 36311766, 2022).
acute promyelocytic leukemia (4 papers, 2016 to 2023). An aggressive form of acute myeloid leukemia (AML), characterized by arrest of leukocyte differentiation at the promyelocyte stage, due to a specific chromosomal translocation t(15;17) in myeloid cells. "In NB4 cells (human acute promyelocytic leukemia cells), irf1 gene is induced more intensively by type II than type I IFN and follows the same pattern of expression than in EC cells." (PMID 31142600, 2019). "In acute promyelocytic leukemia cells, IFNG exhibit a synergistic effect with As203, regulating IRF-1 expression and apoptosis induction." (PMID 38002949, 2023).